IDH1 (isocitrate dehydrogenase (NADP(+)) 1)
Diseases named in the same sentence as IDH1 in open-access papers (continued):
Sharing a sentence is not in itself a finding about the gene and the disease.
glioma (continued). "Subsequently, another subgroup called glioma-CpG island methylator phenotype (G-CIMP), which belonged to the proneural subtype and was tightly associated with IDH1 mutation, was further identified with significant survival benefit for patients." (PMID 25669971, 2015). "NADPH itself can be developed not only as a biomarker, but as a therapeutic target in IDH1 mutant gliomas." (PMID 26008980, 2015). "Somatic mutations in IDH1 and IDH2 have been demonstrated in many human cancers including low grade glioma, glioblastoma, cholangiocarcinoma, chondrosarcoma, and acute myeloid leukemia as recently summarized." (PMID 26097881, 2015). "Mutations in IDH1 or IDH2 are also found in acute myeloid leukemia (~20%), gliomas (60–80%), and cholangiocarcinomas (7–28%)." (PMID 26046462, 2015). "Somatic mutations in genes encoding the enzymes IDH1 and IDH2 have been identified through genome-wide sequencing studies in approximately 70% of grade II and III gliomas, and in approximately 5% of GBMs." (PMID 26948489, 2015). "Moreover, malignant transformation of IDH1-mutated gliomas is of potential interest, as its genomic mechanism under influence of oncometabolite remains unclear, and even higher rate of malignant transformation was reported in IDH1-mutated low grade gliomas than in wild-type IDH1 tumors." (PMID 26524630, 2015). "In gliomas, this mutant IDH1 inhibitor prevents the mutant enzyme from producing D-2HG in a dose-dependent manner, delays tumor growth, and promotes differentiation." (PMID 26368816, 2015). "IDH1-R132H specific IgG were detected in serum of mIDH1-GL261 glioma bearing mice after immunization with the four peptides compared with controls." (PMID 25849072, 2015). "Herein, we explored IDH1/2 mutation (IDH1/2 mut) and its association with Ki-67 expression in primary tumor samples from a large Chinese Glioma Genome Atlas (CGGA) cohort of 703 gliomas." (PMID 26338964, 2015). "The results provided further evidence that additional investigations should be carried out in lower-grade gliomas with wild-type IDH1/2 for better prognostication." (PMID 26369702, 2015). "The IDH1 inhibitor AGI-5198 abrogates the ability of mutant IDH1 to produce the oncometabolite D-2 hydroxyglutarate (D-2HG) in gliomas." (PMID 26368816, 2015). "The majority of IDH1 mutant high-grade gliomas also have MGMT promoter methylation, and IDH1 mutation is a stronger prognostic biomarker than MGMT promoter methylation." (PMID 26646075, 2015). "The IDH1/2 wt group (n = 322 samples), was comprised of 89, 78, and 155 low- moderate-, and high–Ki-67 expression gliomas, respectively." (PMID 26338964, 2015). "A correlation between Par-4 expression and longer median survival is reported in high-grade gliomas that are IDH1 wild type." (PMID 25685660, 2015). "Among 35 patients with WHO grade III gliomas who were operated upon using 5-ALA fluorescence-guided surgery, IDH1 mutations were observed in 24 and intraoperative fluorescence was observed in tumor tissues of 19 patients." (PMID 26008980, 2015). "In relation to molecular characteristics of high-grade gliomas, we correlated IMP3 protein expression with IDH1 mutational and MGMT methylation status." (PMID 25695077, 2015). "An integrated genomic analysis found recurrent heterozygous mutations in the active site of IDH1 and IDH2 isoforms in high proportion of low-grade glioma and acute myeloid leukemia (AML) patients." (PMID 26130389, 2015). "We next studied the correlation between IDH1 and the prognosis of low-grade glioma in our cohort (20 with Grade II and 30 with Grade III, 50 total)." (PMID 26485760, 2015).
glioma (continued). "The aim of this study was to validate the frequency of IDH1 mutation in gliomas in the Mosul city and to correlate the IHD1 positivity with the type and grades of gliomas, and with age and sex of the patients." (PMID 27275230, 2015). "In adult gliomas, the secondary glioblastoma and the low-grade astrocytoma had the greatest values of IDH1 positivity (88.88% and 62.5% respectively), followed by oligoastrocytoma/oligodendroglioma (50.0%), and anaplastic astrocytoma (47.36%)." (PMID 27275230, 2015). "Twenty-seven studies provided data concerning the association between IDH1/2 mutations and PFS of glioma patients." (PMID 26220714, 2015). "Difference in age distribution of IDH1 positivity between adult and pediatric gliomas is statistically highly significant (p<0.001)." (PMID 27275230, 2015). "We propose that NADPH is the key mediator in the varying 5-ALA fluorescence observed between wild type and mutant IDH1 malignant glioma cells." (PMID 26008980, 2015). "The present work was the first study in Iraq to assess the immunohistochemical status of IDH1 mutant in various types and grades of gliomas." (PMID 27275230, 2015). "In a previous study, we reported a high frequency of +7 and −10q CNAs among patients with IDH1 wild-type gliomas." (PMID 26558387, 2015). "There were 381 samples in the IDH1/2 mut group, which included 250, 79, and 52 low- moderate-, and high–Ki-67 expression gliomas, respectively." (PMID 26338964, 2015). "After a few passages of the glioma tissue obtained from a 64-year-old wild-type IDH1 GBM patient, cells were mechanically dissociated into single cells and then placed individually in uncoated 96-well plates and cultured in the presence of EGF and FGF." (PMID 25623281, 2015). "By RT-PCR on explanted gliomas we found that the expression of IDH1 was significantly reduced over the time, from 48.8 ± 1.3 on day 20 to 24. ± 0.4 on day 30 (p < 0.001)." (PMID 25849072, 2015). "To verify the relationship between IDH1 mutations and 5-ALA fluorescence, we established human U87 MG glioma cells that stably express R132H mutant (IDH1R132H) or wild type (IDH1WT) IDH1, using lentiviral vectors." (PMID 26008980, 2015). "Gliomas with an IDH1/2 mutation show upregulation of HIF1α, whereas PHD activity is inhibited in artificial mutant IDH1 cell lines." (PMID 25895133, 2015). "Since glioma cells transfected with mutant IDH1 need 20 passages to show an effect on methylation, we treated the mutant IDH1 cell lines JJ012, HT1080 and the IDH1/2 wildtype cell line CH2879 for up to 20 passages." (PMID 25895133, 2015). "Fifty-four and twenty-seven studies investigated the association between IDH1/2 mutations and OS/PFS respectively in patients with glioma." (PMID 26220714, 2015). "IDH1/2 mutations were first reported in 2009, occurring in about 80% of grade II–III gliomas and secondary glioblastoma multiforme (GBM)." (PMID 26338964, 2015). "Mutations in isocitrate dehydrogenase 1 (IDH1) and IDH2 are found in a subset of benign and malignant cartilage tumors, gliomas and leukaemias." (PMID 25895133, 2015). "IDH1 mutation, MGMT promoter methylation, and 1p/19q co-deletion are the three molecular markers included today in routine assessment of gliomas due to their diagnostic, prognostic, or predictive value." (PMID 25977882, 2015). "We analyzed the relationship between overall survival (OS) and the presence of IDH1/2 and TERT promoter mutations in a panel of 473 adult gliomas." (PMID 24722048, 2014). "To define the co-occurrence of IDH1/2 mutations and the presence of TERT promoter mutations, we determined the status of IDH1 and IDH2 mutations in the same cohort of 473 gliomas and identified mutations in 47.9% (227/473) of tumors." (PMID 24722048, 2014).
glioma (continued). "At least 8 different mutations of IDH1 and IDH2 are known in gliomas, at the IDH1 R132 and IDH2 R172 loci." (PMID 25376594, 2014). "Glioma CpG island methylator phenotype GBM has been shown to be associated with younger patients, with IDH1 mutations and an improved prognosis, clustering in the TCGA proneural subgroup." (PMID 24716189, 2014). "In summary, in the largest randomised trial in chemonaïve patients with recurrent high grade glioma we were able to demonstrate the independent prognostic significance of IDH1/2 and MGMT methylation status, and potentially PTEN status, for survival." (PMID 24952577, 2014). "Four distinct subgroups of Grade III gliomas were identified when stratified by the combination of the TERT promoter and IDH1/2 mutation status (log-rank p=0.0008)." (PMID 24722048, 2014). "The genes for IDH1 and IDH2 carry specific mutations in 70%–80% of low-grade gliomas, in approximately 50% of anaplastic gliomas, and in more than 5% of glioblastomas." (PMID 24511544, 2014). "Surprisingly, 2-HG shows a 100-fold increased concentration in glioma and acute myeloid leukemia's (AML) patients with IDH1 or IDH2 missense mutations." (PMID 25232952, 2014). "We have investigated the mutational status of IDH1 and IDH2 in a cohort of 1305 glioma patients and correlated it with the genomic profile and the outcome." (PMID 24877111, 2014). "Here, we have assessed the characteristic variance between IDH1/2 and TERT promoter mutations among several glioma subtypes that help refine the diagnosis of gliomas." (PMID 24722048, 2014). "Since mutant IDH1 has been pursued as an anticancer target in glioma, it is conceivable that HCC patients carrying the R132 mutation can also benefit from such IDH1 inhibitors." (PMID 25159915, 2014). "Aberrations in both IDH1 and IDH2 genes have been associated with better prognosis in glioma patients of various grades." (PMID 24868540, 2014). "The concept of oncometabolite was established by the studies that mutations of isocitrate dehydrogenase 1 (IDH1) and IDH2 generate a novel metabolite 2-hydroxyglutarate (2-HG) that exhibits oncogenic activity in acute myeloid leukemia and glioma." (PMID 25060643, 2014). "To demonstrate the accuracy of the IDH1/2 PCR assay on clinical routine glioma samples, we examined the concordance between the IDH1/2 PCR results and results obtained with the current IDH1 R132H immunostaining and Sanger sequencing technologies." (PMID 24889502, 2014). "In the present study, three cell lines stably expressing wild-type IDH1 (wIDH1), mutated IDH1 (mIDH1) and enhanced green fluorescent protein (EGFP) were constructed for the study of their effects on the biological behavior of glioma cells." (PMID 24520288, 2014). "Mutations have been found not only in IDH1 and IDH2, predominantly in gliomas, but also in leukemia samples and very rarely in other cancers." (PMID 24868540, 2014). "DNA methylation identifies a subset of PN tumors with glioma CpG island methylator phenotype (GCIMP) that are younger, longer surviving and tightly associated with IDH1 mutations." (PMID 24984002, 2014). "Our study is in agreement with studies in glioma cell lines stably transfected with IDH1-R132H-V5, where reduced proliferation and cell migration in vitro and in vivo were reported." (PMID 25277207, 2014). "We also strongly recommend the evaluation of IDH1 and IDH2 gene mutations as useful tool for the differential diagnosis between WHO I° LEAT and WHO II° gliomas." (PMID 24858213, 2014). "Utilizing a combined analysis of IDH1/2 and TERT promoter mutations in adult glioma, we have derived a greatly expedited and simplified genetic signature of three common glioma subtypes, namely Grade II-III astrocytomas, oligodendrogliomas, and GBMs." (PMID 24722048, 2014).
glioma (continued). "Recent studies showed that inhibition of mutant IDH1 delays growth of glioma cells and induces cellular differentiation in leukemia, which shows possibility of a potential application as a therapy for cancer." (PMID 25232952, 2014). "This set of highly correlated genes also includes IDH1 (Isocitrate Dehydrogenase 1), which has been proposed as a potential therapeutic target in gliomas." (PMID 24947308, 2014). "As observed, within Grade III and IV gliomas separately, tumors with mutations in both TERT and IDH1/2 had the best median OS (oligodendroglioma signature), followed by those with an IDH1/2 mutation only (Grade II-III astrocytoma and secondary GBM signature)." (PMID 24722048, 2014). "Downregulated isoforms of IDH3 were also noted, and IDH1 and IDH2 mutations have recently been reported in gliomas." (PMID 24728830, 2014). "Mutations have also been identified in isocitrate dehydrogenase 1 (IDH1) that inhibit IDH1 catalytic activity in glioma, thereby reducing the production of α-KG, increasing HIF-1α and presumably, tumorigenesis." (PMID 25420025, 2014). "These 1,976 tumors represent only the immunohistochemical and sequence verified IDH1 mutant cases out of the whole collection of glial tumors in our department." (PMID 24529257, 2014). "The study clearly demonstrates that in patients with recurrent high-grade glioma treated with either TMZ or PCV, IDH1/2 mutation and MGMT methylation levels are of prognostic value independent of tumour grade and of other clinical prognostic factors." (PMID 24952577, 2014). "Frequent mutations in isocitrate dehydrogenase 1 and 2 (IDH1 and IDH2) and the promoter of telomerase reverse transcriptase (TERT) represent two significant discoveries in glioma genomics." (PMID 24722048, 2014). "Promisingly, 5-azacitidine has recently been shown to be effective in reducing selected promoter methylation, tumor growth, cell proliferation and inducing differentiation in an in vivo primary xenograft IDH1 mutant glioma." (PMID 25012071, 2014). "When with the development of sequencing technologies, researchers found mutations in IDH1, IDH2 (isocitrate dehydrogenase) in medium-grade glioma and acute leukemia." (PMID 25232952, 2014). "For example, IDH1 and IDH2 mutations are associated with much better glioma patient prognosis, and the BRAF mutation was associated with more favorable acral lentiginous melanoma prognosis." (PMID 25332145, 2014). "For example, IDH1 and IDH2 mutations are associated with better glioma patient prognosis, and Braf mutations are associated with better prognosis in acral lentiginous melanoma." (PMID 25332145, 2014). "No mutations of IDH3, which normally catalyse the same reaction as IDH1/IDH2 (but use NAD+ as substrate) have been noted in gliomas, so the consequence of its downregulation can only be extrapolated from reports on IDH1/IDH2." (PMID 24728830, 2014). "As these gliomas, wildtype for both TERT promoter and IDH1/2 mutations, represented a clinically distinct unit further investigation is required to delineate critical driver mutations in this subset of gliomas." (PMID 24722048, 2014). "IDH1 mutations affected 72.5% (316/436) grade II, 63.7% (251/394) grade III, and 8.8% (42/475) grade IV gliomas." (PMID 24877111, 2014). "Further studies for testing EB1 in addition to other biomarkers such as MGMT status and IDH1 mutation are warranted in patients with GBM and other high grade gliomas to confirm EB1 prognostic role." (PMID 25473893, 2014). "Recently homozygous IDH1 aberrations in gliomas were reported for the first time in 2 patients with secondary GBM and in a patient with astrocytoma." (PMID 24868540, 2014).
glioma (continued). "In contrast, wild type IDH1 gliomas exhibited low levels of methylation at all targets analyzed, consistent with reported data." (PMID 24077805, 2013). "A common feature of IDH1 and IDH2 mutations observed in AML and gliomas, however, is the apparent acquisition of enzymatic activity not shared by wild-type enzyme, known as neomorphic activity." (PMID 23847760, 2013). "To study the effect of DAC on mutant IDH1 expressing gliomas, we utilized glioma tumor spheres that carry an endogenous heterozygous R132H mutation (TS603)." (PMID 24077826, 2013). "To date, little is known about the role of IDH1 and its clinical implications in the processes of glioma progression, particularly in Chinese patients." (PMID 23840696, 2013). "In our study, IDH1 mutation was associated with longer OS and PFS in 53 patients suffering from various grades of glioma, particularly in astrocytic tumors." (PMID 23840696, 2013). "Excess accumulation of d-2HG has been demonstrated in a subset of cases of glioma and AML with IDH1 or IDH2 mutations." (PMID 23847760, 2013). "In support of the results of in vitro enzymatic analyzes, d-2HG levels are 100-fold higher in cases of glioma and AML that carry IDH1 or IDH2 mutations as compared with tumors with wild type IDH." (PMID 23847760, 2013). "Previous reports were mainly focused on analysis of IDH1 status in primary gliomas or secondary gliomas." (PMID 23840696, 2013). "IDH1 mutation is described in more than 70% and 50% of grade II and III glioma tumors, but only 5% in primary GBM." (PMID 24217114, 2013). "This analysis defined two highly recurrent genetic signatures in gliomas: IDH1/ATRX (I-A) and IDH1/CIC/FUBP1 (I-CF)." (PMID 24202337, 2013). "Somatic point mutations at hot-spot codons Arg132 (R132) of the IDH1 gene and Arg172 (R172) of the IDH2 genes were identified in 61 of 178 gliomas (34.3%)." (PMID 24083241, 2013). "In the present study, we investigated the mutation status of IDH1 and IDH2 in 53pairs of primary and recurrent gliomas." (PMID 23840696, 2013). "The mutations of nicotinamide adenine dinucleotide phosphate- (NADP-) (+) dependent IDH1 were frequently identified in WHO grade II or III gliomas." (PMID 24324372, 2013). "In our study,we investigated the IDH1 and IDH2 status of 53 pairs of primary and recurrent gliomas by direct sequencing and anti-IDH1-R132H immunohistochemistry." (PMID 23840696, 2013). "Our findings demonstrate the efficacy of DNA demethylating agents in targeting glioma-initiating cells and highlight the differential response of IDH1 mutant versus IDH1 wild-type glioma cells to low doses of DAC." (PMID 24077826, 2013). "Although it is very likely that these drugs have the potential to help patients with IDH1 mutant gliomas, the optimal demethylating drug, patient population, dosing strategy, delivery and drug combinations have yet to be determined." (PMID 24077805, 2013). "Mutations in the metabolic enzyme isocitrate dehydrogenase 1 (IDH1) are found in >70% intermediate grade gliomas, a disease which eventually progresses to high-grade glioma within 10 years." (PMID 24077826, 2013). "IDH1 mutations are particularly frequent in grade II and III gliomas where they are found in up to 70% of the patients." (PMID 23634848, 2013). "Isocitrate dehydrogenase isoforms 1 and 2 (IDH1 and IDH2) mutations have received considerable attention since the discovery of their relation with human gliomas." (PMID 23894344, 2013). "On the contrary, growth was more modestly impaired in the IDH1-wild-type TS667 glioma xenografts when compared to the IDH1-mutant expressing TS603 glioma xenografts." (PMID 24077826, 2013). "Recently, somatic mutations in the isocitrate dehydrogenase 1 (IDH1) or IDH2 gene have been identified in the majority of WHO grade II and III gliomas and secondary GBMs." (PMID 23762610, 2013).